CD4 (CD4 molecule)
Diseases named in the same sentence as CD4 in open-access papers (continued):
Sharing a sentence is not in itself a finding about the gene and the disease.
infection (continued). "Following PBMC stimulation with CD3-CD28 beads, an increase in CD4+ lymphocyte IL-2R expression and a reduction in IL-7R expression were consistent between healthy volunteers, pre-operative and post-operative samples (in patients with and without post- operative infections) (p < 0.05 for all)." (PMID 38655251, 2024). "Although IL-17 producing CD4+ T cells tended to be higher overall in individuals with versus without Sh infection, the greatest differences was noted between individuals with Sh infection with genitourinary pathology compared to those with Sh infection but without pathology." (PMID 39250522, 2024). "Moreover, productive in vitro infection of activated CD4+ T cells, but not CD8+ T cells, was obtained in an angiotensin-converting enzyme (ACE2)-independent manner, suggesting lymphocyte function-associated antigen 1 (LFA-1) or CD4 as alternative receptors." (PMID 38787201, 2024). "Notably, ETO-treated mice also exhibited an elevated proportion of CD4+ and CD8+ T-lymphocytes, suggesting that FAO blockade not only alters immune cell composition but also enhances protective immunity against TB by modulating infection dynamics within the lung." (PMID 39365825, 2024). "Thus, while the depletion of CD4+ T cells heightened GPCMV viral loads and caused more severe disease in naïve guinea pigs, the depletion of CD8+ T cells was comparably well-tolerated and had no apparent effect on the acute phase of infection." (PMID 39495799, 2024). "However, whether CD4+ T cells are indeed directly involved protection from infection (including asymptomatic or mild and severe infection) as has been suggested in animal studies is not yet clear, but would be valuable to understand." (PMID 38318179, 2024). "Interestingly, this has similarly been proposed in a system where IFN-γ-dependent antibody-mediated protection against pulmonary Francisella novicida infection requires the presence of CD4+ T cells during immune priming by vaccination, but not during the effector phase after infection." (PMID 37654501, 2023). "Indeed, studies specifically evaluating immune memory to SARS-CoV-2 revealed that memory CD4+ T cells and memory CD8+ T cells could be detected 6 months after infection in 90% and 70% of convalescent patients, respectively, and memory B cells in nearly all patients in the same time frame." (PMID 36834949, 2023). "Thus, the scRNA seq studies have shown that the transcriptome of latent HIV-harboring CD4+ T cells favors long-term cell survival, proliferation, and HIV-silencing and may provide targets for effective therapeutic approaches to clear the proviral infection." (PMID 37759517, 2023). "Similarly, CD4 + T cell responses do not reach their peak until days 7–9 post-infection." (PMID 37069680, 2023). "Notably, protection was abrogated regardless of whether the CD4+ T cells were depleted at the time of vaccination or during infection." (PMID 36732332, 2023). "However, the polyfunctional cytokine profiles of CD4+ T cell (p = 0.0097, p = 0.037 for BA.1 and BA.4/5, respectively) and CD8+ T cell (p = 0.0001, p = 0.010, respectively) responses were lower in inactivated vaccine-healthy individuals than those in breakthrough infection individuals." (PMID 37037791, 2023). "The role of this efficient immune response of natural hosts of SIV could not be assessed in this study, as we initiated the CD4-depleting antibody treatment at 21 dpi, i.e., after the innate immune response, to avoid altering virus reservoir seeding during acute infection." (PMID 36813761, 2023). "Interestingly, SARS-CoV-2-specific CD4+ T cells, including those specific for R-derived peptides, in individuals without a history of natural infection were enriched in a TEM phenotype, when compared with bulk CD4+ T cells, while a high proportion also exhibited a TCM phenotype." (PMID 37575243, 2023).
infection (continued). "However, the differences in plasma VL in CD4-depleted dams is largely confounded by the treatment group, as all four AF-negative CD4-depleted animals received passive IgG infusion before infection and all six of the CD4-depleted dams without pre-existing antibody were AF-positive." (PMID 37131785, 2023). "Likewise, mice deficient in CD4+ T cells exhibited less efficient control of parasite growth at the site of initial infection, relative to mice deficient in CD8+ T cells, although both CD4+ and CD8+ T cell-deficient mice ultimately failed to control the resulting systemic infection." (PMID 36695605, 2023). "Finally, by multiplying the subset frequency by the infection frequency, we derived the subset HIV DNA level which reflects the relative contribution of each subset to the measured HIV DNA, i.e., the number of integrated HIV DNA copies in a given subset per million total CD4 cells." (PMID 37783718, 2023). "Considering that memory CD4+ T cells were reported to be essential for larval trapping in secondary Hpb infection, we asked whether VillinCre_STAT6vt would still be protected from secondary infection if CD4+ T cells are absent." (PMID 37018382, 2023). "However, studies conducted on rhesus monkeys using the MPXV model revealed that the depletion of CD4+ T cells or CD8+ T cells from VACV-immune animals prior to the infection with MPXV did not reduce protection against lethal challenge, which was in opposition to the depletion of B cells." (PMID 36986285, 2023). "This transferred immunity is more protective from TAS2010-vaccinated compared with BRD509-vaccinated donors, suggesting CD4+ T cells carried antimicrobial functions very early on, even though the effect of their depletion on systemic bacterial load does not become apparent until later in infection." (PMID 37733817, 2023). "Furthermore, immunization with the model antigen NP-OVA or sheep red blood cells failed to upregulate GzmB in either CD8+ or CD4+ T cells, whereas infection with the vaccinia virus Western Reserve strain (VACV) induced GzmB expression in a subset of both CD4+ and CD8+ T cells." (PMID 37161048, 2023). "In the absence of infection, PBMCs remain as single cell monolayers but upon infection with live M.tb, PBMCs form granuloma-like structures that are up to 15 cell layers thick, contain macrophages, multinucleated giant cells, CD4 + and CD8 + T cells, B cells, NK cells, and intracellular M.tb." (PMID 37864894, 2023). "However, this does not affect the cellular responses of CD8 and CD4 T cells against other infections such as cytomegalovirus or influenza, as these pathogens do not predominantly infect B cells, and their antigens are predominantly presented by other APCs (monocytes and dendritic cells)." (PMID 35894054, 2022). "This suggests that immune reconstitution does not cancel the effect of reaching a low nadir CD4 count in the past, but it is unclear whether this is due to a remaining weak local immunity, or to a lower possibility of infection clearance after months or years of persistence." (PMID 35587503, 2022). "Altogether, these data demonstrate that the onset of the BCG-specific CD4+ T-cell response is similar in both B6- and pMT-10-vaccinated mice, thus supporting the hypothesis that IL-10 overexpression during infection does not significantly impair BCG-mediated immunity." (PMID 35935958, 2022). "Thus, lymphocytes (CD4+ and CD8+ T cells and CD20+ B cells) and NK cells (CD56+) were almost completely resistant to HK-R2, whereas HK and HK-H17R infected these cells at a level of 20 to 40 % (MOI 3) with HK-H17R showing a higher infection rate than HK in CD4+ T cells and NK cells." (PMID 35359920, 2022). "Downregulation of CD4, which is a natural process in the maturation of CD4+ T cells into CD4neg CD8aa+ T-cells in non-progressing hosts and does not seem to lead to any pathologies, appears to be a potential approach to effectively prevent cell infection regardless of co-receptor usage." (PMID 36713371, 2022).
infection (continued). "It has been also observed that the increased infiltration of the CD4+ T cells to the trachea of the chickens after ILTV infection could be as a result of the need to activate or regulate other immune cells through cytokine production, such as IFN-γ, and control the severe infection." (PMID 35632538, 2022). "Moreover, when analyzing the pool of CD4 memory T cells, the cells that were capable of recognizing the epitopes of the three main SARS-CoV-2 structural proteins were predominantly from the Th1 subset, and this was noted already at very early stages after infection." (PMID 35632823, 2022). "Interestingly, CD4 and CD8 T cell activation mostly resolved in the peripheral blood by day 14 PI but CSF CD38 + HLA-DR + CD8 T cell frequency peaked at day 14 PI and remained elevated in 2 of 4 animals (when compared to each animals’ pre-infection level) at day 28 PI." (PMID 35130924, 2022). "Despite this, BCG vaccination does not appear to overcome the migration deficiency of CD4+ T cells primed in an IL-10-enriched environment, as is the case of ESAT-6-specific T cells, which may have a detrimental impact in the long-lasting control of infection." (PMID 35935958, 2022). "In summary, CD4 T cells in Chlamydia-infected T-bet deficient mice show a perturbed immune response with marked inhibition of IFN-γ responses and a prominent shift toward a dominant Th17 response, however this did not increase FRT pathology during primary infection." (PMID 35196366, 2022). "However, similar to macrophages, infection with Mtb mutants lacking nuoG reduced neutrophil life span with the acquisition of fewer Mtb per neutrophil, induced earlier Mtb infected-DC migration to LNs, resulting in the acceleration of CD4+ T cell priming." (PMID 35967869, 2022). "However, these claims have been confounded with data demonstrating that astrocytes are capable of engulfing HIV-1-infected macrophages, providing a more probable explanation of proviral DNA within astrocytes isolated via in situ hybridization assays than infection of CD4-negative astrocytes." (PMID 35975998, 2022). "Similarly, B cell depletion prior to infection with Trypanosoma cruzi reduces subsequent induction of total and parasite-specific CD8 T cells, and B cells are critical in the development of antigen-specific effector and memory CD4 T cell responses to Listeria and Salmonella." (PMID 35371092, 2022). "However, in KO rats following infection with S. japonicum, the significant increase of IL-4-producing CD4+ T cells frequency was only found in the blood but not in the LN and spleens, in which the magnitude of increase between naïve and infected groups was lower than those found in the WT rats." (PMID 35584107, 2022). "Importantly, CD3+CD8+ T cells and NK cells expanded in the patients, which may have contributed to the lack of severe infection during the period of CD4+ aplasia." (PMID 36172388, 2022). "Since cell-cell fusion infection overcomes both entry and post-entry blocks for most R5 and X4 tropic strains, including those defined as R5 or X4 T-tropic by cell-free assays, it may be a prevalent mode for HIV-1 spreading in vivo in MΦ and related myeloid cells in tissues rich in CD4+ T cells." (PMID 35622876, 2022). "Moreover, we find that the number and nature of exposures (rather than the order of infection and vaccination) shape the spike immune response, with spike-specific CD4 T cells displaying a greater polyfunctional potential following hybrid immunity compared with vaccination only." (PMID 36584684, 2022). "Indeed, stimulation with Mtb antigens Early Secretory Antigenic Target (ESAT)-6 and Culture Filtrate Protein (CFP)-10 induces IFN-γ and TNF-α production by the CD4+ and CD8+T cells that may provide tools to study the role of these early responses in protection from a fatal infection." (PMID 34484203, 2021).
infection (continued). "Furthermore, the CD4 T-cells steadily decline in concert with the total adaptive (CD8) immune population, until a weakened immune system no longer can control the prevalent multi-epitope resistant virus strains, and viral load rapidly grows in the last stage of infection." (PMID 34691023, 2021). "Multicolor flow cytometry was utilized to analyze the CD4+ and CD8+ T cell populations and their intracellular production of the cytokines IFNγ, TNF, and IL2 (single, double, and triple combinations) associated with both the lethal and nonlethal murine models of infection." (PMID 34287349, 2021). "This suggests that at least part of the CSF HIV reservoir may be generated by either an infection mode not requiring drug resistance for viral replication, or by latently infected CD4+ T cells trafficking to and releasing HIV in the CSF without extensive viral replication taking place." (PMID 34555123, 2021). "Using CD4 data alone might not be sufficient to estimate time point of infection." (PMID 33474833, 2021). "This important role of CD4+ T cells in the control of primary SARS-CoV-2 infection might also continue for the development of long-term immunity, reflected by the here reported trend to increased SARS-CoV-2-specific and cross-reactive HLA-DR-restricted T cell responses at six months post infection." (PMID 33723016, 2021). "Moreover, IL-10-nonproducing memory CD4 T cells rapidly upregulated IL-10 expression during recall, with reported potent inhibitory effects on CD4 T cell effector functions during secondary infection." (PMID 33529242, 2021). "To explore whether PD-1 signaling mediated effector T cell exhaustion and facilitated persistent infection in infancy or adulthood, we detected the expression of PD-1 on CD4+ or activated CD4+ T cells after lethal P.y17XL and non-lethal P.y17XNL infection by flow cytometry." (PMID 33430765, 2021). "While the strain of V. cholerae causing infection and subsequently the virulence factors utilized during the infection may influence the CD4+ differentiation, data presented here do not indicate differences in responses, as one major difference between the strains used is the presence of CT." (PMID 34888255, 2021). "However, absolute CD8+ CD3+ T-cell levels may be increased in HIV-positive patients with untreated infection, with high variability in the levels in patients on ART, resulting in either a decrease in, or increased variability, in mucosal CD4 T-cell percentages." (PMID 34135912, 2021). "NMI infection induced a significant body weight loss in unimmunized WT and NMII-immunized B cell-deficient and T cell-deficient mice at different times post challenge, but there was no body weight loss in NMII-immunized WT, CD4+ T cell-deficient, and CD8+ T cell-deficient mice." (PMID 34795669, 2021). "However in vivo infection of CD4+ but not CD8+ T cells is not supported by published studies." (PMID 35965490, 2021). "As HSV-1 typically accedes to the hindbrain via the trigeminal ganglia (TG) in i.n. models of infection, we first examined the TG at day 4 p.i. and the brainstem at day 5 p.i, and found no major differences in the number of myeloid, CD4+ or CD8+ T cells between Rel+/+ and RelC307X groups." (PMID 34707143, 2021). "Furthermore, SjS patients with either serological evidence of past EBV infection or recent infection/reactivation presented higher values of CXCR3+ CD4+ T cells (Th1) and CXCR3+ CXCR5+ CD4+ T cells (Tfh1) compared to those without serological evidence of active infection." (PMID 33603079, 2021). "Therefore, we considered whether CD4+ T cell help was needed to develop functional CD8+ T cell responses after i.n. infection, rather than to directly control TKO-MCMV." (PMID 33508041, 2021).
infection (continued). "Moreover, so-called recently activated CXCR5+CD4 T cells, identifiable by upregulation of programmed-death receptor-1 (PD1), Ki-67 protein (Ki-67) and ICOS expression, appear in blood in response to specific immune activation post vaccination or during infection." (PMID 34446066, 2021). "As the HeLa cell model may not fully recapitulate HIV-1 trafficking or infection in primary CD4+ T cells, infectivity of WT HIV-1 and CA mutants was performed in phytohemagglutinin (PHA)-stimulated primary human peripheral blood mononuclear cells (PBMC) from 3 donors." (PMID 33758083, 2021). "Moreover, a role of the viral m138 protein participating in immune evasion of CD4+ T cells could be observed in spleen and lungs when comparing data from MCMVwt and MCMVΔm138 infections, although this was not the case in the salivary glands." (PMID 33459589, 2021). "Thus, it appears as if memory CD4 T cells reactive with peptides in the RBM may reflect the immunological history of the individual that, as evidenced by this case, can be unrelated to infection by other coronaviruses." (PMID 33571241, 2021). "Furthermore, in naïve mouse models during infection, mapping by peptides and virus-like particles of structural (S, N, M, E) and selected ORFs (ORF3a, ORF6, ORF7a, ORF8, ORF9b, and ORF9c) showed a similar immunodominance of CD4+ T cell responses toward S, N, and ORF8-derived peptides." (PMID 35004764, 2021). "At 2wk post-challenge, the PBS (control) group had higher CD4+ T-cells frequency, indicating that the non-vaccinated group could still be trying to eliminate the infection at 2 wk post-challenge, as supported by our serology findings, whilst the CNP vaccinated birds have cleared the SE infection." (PMID 33822791, 2021). "Also, the absence of CD4+ T cells in the chronic phase of infection deterred CNS recovery and aggravated RSA59 induced axonal blebbing and demyelination, along with a significantly high accumulation of CD11b+ M2 type microglia/macrophages in the demyelinating plaques." (PMID 34898656, 2021). "As the menstrual cycle is not the result of an infection, it is reasonable to suppose that a lack of archetypal CD4 T cell activation through antigen-specific recognition indicates little to no change within the target T cell population that might increase HIV infection risk in the FRT." (PMID 34229275, 2021). "Whether identifying and treating HIV at the earliest stages of infection (within one month) reduces the frequency of clinical immunologic non‐response is not known, though improved CD4 recovery has been described in ART initiation within four to six months of infection or seroconversion." (PMID 32949118, 2020). "The low levels of infection observed in myeloid cells, even in the presence of Vpx, could be explained by an inability of Vpx to overcome SAMHD1 completely, other post-entry restriction factors, or by CD4 and/or coreceptor densities that are too low to facilitate efficient entry." (PMID 32992787, 2020). "Lastly, it might be that adoptive transfer of an isolated T cell subset such as CD8+ Tc17 cells is not enough to protect the mice from infection and that other T cell subsets such as CD4+ Th17 cells or IFNγ-producing Th1 and Tc1 cells are required for protection." (PMID 32582196, 2020). "Since autophagy is necessary for HIV to establish a productive infection, and the pharmacological induction of autophagy inhibits HIV release (42, –, 50), we next determined whether TNP influences HIV p24 antigen accumulation in the supernatants of productively infected macrophages and CD4+ T cells." (PMID 32934078, 2020). "Furthermore, most of the patients (81.3%) correctly identified the eligible patients for CrAg screening based on CD4 count, and 75.5% of them correctly identified pre-emptive treatment as treatment of patients with serological or imaging evidence of infection even when clinical disease is absent." (PMID 32628714, 2020).